SMG1 (SMG1 nonsense mediated mRNA decay associated PI3K related kinase)
Diseases named in the same sentence as SMG1 in open-access papers (continued):
Sharing a sentence is not in itself a finding about the gene and the disease.
tumor (continued). "As a control, we also included a tumor clone derived from a single tumor cell by dilution after sorting, containing a unique type of CRISPR-mutation in SMG1 gene as well as complete SMG1 blockade in the B16/F10 cell line." (PMID 36443756, 2022). "Given the potential role of SMG1 in tumor immunity and the fact that SMG1 expression varies in tumor samples, we stratified the patients based on changes in SMG1 expression (ΔSMG1) after anti-PD-1 antibody treatment (Pembrolizumab)." (PMID 36443756, 2022). "Bearing in mind this criterion, the tumor samples from patients that upregulated SMG1 expression (+ΔSMG1) after treatment with Pembrolizumab were characterized by a lower clonal expansion." (PMID 36443756, 2022). "A1411 aptamer with a broad spectrum of tumor recognition is used to target SMG1 inhibition via siRNA delivery in different tumor models." (PMID 35991316, 2022). "Meanwhile, a growing body of evidence has confirmed that SMG1 acted as a tumor suppressor in various human cancers." (PMID 34595165, 2021). "Subsequent assays showed that CircPPP1CB was aberrantly lower and served as a tumor suppressor via the miR-1307-3p/SMG1 axis in human BC." (PMID 34595165, 2021). "Suppressor of morphogenesis in genitalia 1 (SMG1) is an important member of phosphoinositide 3-kinase related kinase family, which plays a tumor-suppressive role in human malignancies." (PMID 34784955, 2021). "Both LCOR and SMG1 protein are known to function as a tumor suppressor in multiple cancers and mediate the repression of tumor growth by regulating oncogenic proteins involved in cell cycle." (PMID 31761786, 2019). "IHC staining on tumor sections showed a marked increase in SMG1 and E-cadherin protein levels and a decrease in Snail, p-4EBP1, Vimentin and Ki-67 protein levels in the antagomir-18a treated group." (PMID 31659158, 2019). "By contrast, a decreased number of SMG1-expressing cells was observed at the edges compared with the central portions of the tumors, supporting the suppressive role for SMG1 in advancing tumor growth in NPC." (PMID 31659158, 2019). "In summary, these findings illustrate that SMG‐1 is suppressed by miR‐192 and‐215 and functions as a tumor suppressor in GC by inactivating Wnt signaling and suppressing EMT." (PMID 29239144, 2018). "SMG‐1,a member of the phosphoinositide kinase‐like kinase family, functioned as a tumor suppressor gene." (PMID 29239144, 2018). "This approach led to a significant reduction of Upf2 and Smg1 expression and the up-regulation of tumor rejection antigens, thereby inhibiting tumor growth in vitro and in vivo." (PMID 26863567, 2016). "In conclusion, our results indicate that SMG1 acts as a potential tumor suppressor with epigenetic regulation in AML." (PMID 25257528, 2014). "In conclusion, our results indicate that SMG1 acts as a potential tumor suppressor with epigenetic regulation and highlights a new approach for the demethylating treatment of DAC in AML." (PMID 25257528, 2014). "Recently, SMG1 was suggested as a novel potential tumor suppressor gene, particularly in hypoxic tumors." (PMID 25257528, 2014). "Recently, SMG1 was suggested as a novel tumor suppressor gene, though its role as a NMD effector has been well known." (PMID 25257528, 2014). "The identification of a candidate tumour suppressive function for SMG-1 further validates the planarian system as a source of novel insights relevant to human disease processes." (PMID 22479207, 2012). "NMD-inhibition by siRNA targeting of NMD regulatory genes SMG1 or UPF2 has recently been shown capable of inducing protective in vivo immune responses to tumour cells transfected with an NMD-sensitive target antigen." (PMID 21209843, 2010). "In these studies, SMG-1 was shown to exhibit tumor suppressive properties." (PMID 39506517, 2024).
tumor (continued). "Tumor samples with higher SMG1 expression levels displayed more abundance of CD8 naïve phenotype while all the other T-cell subtypes were similar or much more abundant in the SMG1-low tumors." (PMID 36443756, 2022). "To assess whether SMG1 expression can condition the outcome of immune responses, we implanted tumor cells with similar OT-I activation capability (as measured in vitro) in the same mice but on their opposite flanks." (PMID 36443756, 2022). "As we observed that tumor samples with low SMG1 expression were more abundant in exhausted CD8 lymphocytes we decided to evaluate whether the inhibition of NMD could improve the outcome of anti-CTLA-4 and anti-PD-1 (ICB) therapy in 4T1 tumors." (PMID 36443756, 2022). "Targeting inhibition of SMG1 was assessed as well in Panc02 and B16/F10 tumor cells pre-transfected with SMG1-psiCHECK reporter luciferase system, and we observed a significant reduction of luciferase signal proportional to the level of RNAi-mediated inhibition in both cell lines." (PMID 35991316, 2022). "The cross-presentation and TCR-signaling pathways identified through the GSEA analyses indicated that they were inversely correlated with SMG1 expression in most tumor types; confirming the importance of SMG1 values in tumor immunity, thus supporting the scRNAseq analysis and the mouse models." (PMID 36443756, 2022). "We identify the existence of a molecular mechanism shielding the tumor from immune attack regulated by the IL-6/STAT3/SMG1 axis that prevents antitumor immune responses: a new immunoediting process to silence potent neoantigens by immune intrinsic pathways that affect the activity of NMD." (PMID 36443756, 2022). "As the BRCA study included the detailed scRNAseq immune dataset, we performed a precise analysis of the different T-cell subpopulations after dimensional reduction (UMAP) and separation in the group of patients based on low SMG1 and high SMG1 expression in the tumor cells." (PMID 36443756, 2022). "SMG1 also suppressed tumor angiogenesis in human umbilical vein endothelial cells (HUVECs)." (PMID 34595165, 2021). "As SMG1 functioned in oxidative stress resistance during tumour formation and inflammation, we then attempted to whether cicrVMA21 played a role in the resistance of oxidative stress." (PMID 32827242, 2020). "Although there were no tumour samples available to test for somatic inactivating second hit mutations, lymphocyte DNA was available to evaluate for segregation of the SMG1 variants with PC in two families with European ancestry." (PMID 31469826, 2019). "Vimentin (increased for the group >200 colonies) is considered a negative prognostic factor in AML, whereas SMG1 (decreased for the group >200 colonies) is a potential tumor suppressor in hypoxic tumors and associated with regulation of AML cell proliferation." (PMID 30634713, 2019). "Interestingly, weaker staining of SMG1 was observed in the edges of the tumor masses than in the centers, in contrast with the staining of Ki-67, Snail and Vimentin, which was stronger in the tumor edges than in the centers." (PMID 31659158, 2019). "Recently, SMG‐1 was shown to exhibit tumor‐suppressive properties." (PMID 29239144, 2018). "Moreover, low expression levels of SMG‐1 in GC samples supported a tumor‐suppressive role in GC and correlated with clinical parameters." (PMID 29239144, 2018). "Thus, SMG‐1 has been suggested as a tumor suppressor gene, although its role as an NMD effector has been well documented." (PMID 29239144, 2018). "In sum, this result suggest that high basal level of SMG1 expression in the tumor in pre-treatment as well as upregulation of SMG1 (+ΔSMG1) after ICB might restricts the expansion of T cells infiltration in the tumor." (PMID 36443756, 2022).
tumor (continued). "Importantly, the pathway of IL6ST was directly correlated with SMG1 expression in most tumor types in line with previous observations and indicating that IL-6 axis could be an inducer of SMG1." (PMID 36443756, 2022). "Thus, the tumor suppressor role of SMG1 was investigated in AML." (PMID 25257528, 2014). "To recapitulate the effect of NMD activity in the outcome of tumor progression, we generated different tumor cell lines with their NMD machinery compromised by blocking key NMD factors -SMG1, UPF1, UPF2- via CRISPR." (PMID 36443756, 2022). "To further validate the relevance of IL-6/STAT3 axis in the control of SMG1 expression and thus of the NMD activity, we used different tumor-cells expressing the NMD luciferase reporter plasmid cultured in the presence of hyper-IL6." (PMID 36443756, 2022). "It has been discovered that SMG1 expression negatively correlates with HPV (Human Papillomavirus) status in cancer cell lines and tumours." (PMID 32213869, 2020). "Depletion of SMG-1 in HPV-negative HNSCC cells resulted in increased radiation sensitivity, while SMG-1 overexpression protected HPV-positive tumour cells from irradiation." (PMID 32213869, 2020). "Expression levels for NMD-related factors (UPF1, UPF2, UPF3A, UPF3B, SMG1, SMG2, SMG6, and SMG7) were calculated from microarray-derived datasets of primary tumor samples (n = 40 MSI, n = 48 MSS) and matched normal colon samples (n = 95)." (PMID 30228267, 2018). "Looking into the expression of SMG1, IL6ST (IL-6 signal transducer) and STAT3 in single tumor cells from those datasets, we observed that higher expression of SMG1 co-localized in the same cells that had higher levels of IL6ST, being such association very strong with the STAT3 factor as well." (PMID 36443756, 2022). "To ensure that the SMG1 inhibition was not affecting the immunogenicity of the tumor by other mechanisms not directly related to the antigen expression under NMD control, we first confirmed that MHC-I expression was not altered in SMG1KD tumors." (PMID 36443756, 2022). "Taken together, our results demonstrated that circPPP1CB participates in tumor growth, metastasis, and EMT process by interacting with the miR-1307-3p/SMG1 axis, and that circPPP1CB might be a novel therapeutic target and diagnostic biomarker in human BC." (PMID 34595165, 2021). "Importantly, we identified SMG1 as a potential negative regulator of EMT and cell invasion in NPC, suggesting a tumor-suppressive role of SMG1 in NPC." (PMID 31659158, 2019). "The results showed that SMG1 was significantly downregulated in tumor tissues compared with non-tumor tissues (P < 0.001)." (PMID 31659158, 2019). "In addition to cell‐autonomous effects of inhibition of SMG1/NMD, inhibition of NMD may increase tumor antigens and immunogenicity of tumors, thereby potentially stimulating an antitumor immune response." (PMID 36400430, 2023). "We used immunohistochemistry (IHC) to detect tumor SMG-1 protein expression in these patients and divided all patients into two groups accordingly: SMG-1 positive (n=11) and SMG-1 negative (n=25)." (PMID 39506517, 2024). "Inhibition of SMG1, independent of TORK and DNA‐PK, appeared to be the prime mode of CC‐115‐induced caspase and BAX‐ and BAK‐dependent cell death in certain tumor cells." (PMID 36400430, 2023).
haematopoietic cancer (2 papers, 2019 to 2022). "Overall, our data demonstrated that combined loss of Atm expression and decreased Smg1 expression increases haematopoietic cancer development." (PMID 31565865, 2019).
infection (2 papers, 2015 to 2025). The state of being infected such as from the introduction of a foreign agent such as serum, vaccine, antigenic substance or organism. "Similarly, two MAPK genes (MPK6 and MSRMK2) and two MAPK(K) genes (OsMKK1 and SMG1-OsMAPKK4) showed consistent upregulation across all the transcriptomes under MOR infection." (PMID 40429762, 2025).
hematologic malignancies (1 paper, 2023). "Effects of SMG1 inhibition were tested in in vivo models, using CC‐115 as it has already been tested in humans in advanced solid and hematologic malignancies, and SMGi compound cannot be applied in vivo." (PMID 36400430, 2023).
immune disease (1 paper, 2022). "Synaptotagmin XVII, membrane transport proteins, Ca2+ sensing protein and SMG1 are also encoded by phosphatidylinositol 3-kinase-related kinase, thereby regulating immune disease progression, metabolism and contraction." (PMID 35514959, 2022).
SMG1 also shares sentences with these, for which no sentence is quoted: lung adenocarcinoma (2 papers); varicocele (2); acute kidney injury (1); Alzheimer disease (1); anaemia (1); autism (1); glioma (1); head and neck cancer (1); intervertebral disc degeneration (1); kidney injury (1); leukemia (1); lymphoma (1); malaria (1); Myelodysplasia (1); neuroblastoma (1); non-small cell lung carcinoma (1); osteosarcoma (1); pancreatic adenocarcinoma (1); papillary lung adenocarcinoma (1); Parkinson disease (1); Ullrich's disease (1); Waldenström's macroglobulinemia (1).